IL10 (interleukin 10)
Diseases named in the same sentence as IL10 in open-access papers (continued):
Sharing a sentence is not in itself a finding about the gene and the disease.
Sepsis (continued). "Finally, in another study of murine sepsis, administration of trifuoroperazine, an antipsychotic agent, reduced organ damage and mortality through inhibition of pro-inflammatory cytokine surge, while reducing IL-10 levels." (PMID 35271683, 2022). "Interestingly, tamarixetin protected mice from sepsis by stimulating the secretion of the IL-10." (PMID 36361685, 2022). "Indeed, the increased plasma cells may possess an immunoregulatory profile, as recent studies have found that sepsis expands the population of IL-10-producing plasmablasts that can exacerbate immunosuppression." (PMID 36425582, 2022). "Furthermore, we investigated serum IFNγ/IL10 of propensity score matched patients from the placebo arm of the randomized placebo-controlled trial of Sodium Selenite and Procalcitonin-guided antimicrobial therapy in Severe Sepsis (SISPCT)." (PMID 33767693, 2021). "Interestingly, cytokine network analyses have revealed a network formed by IL‐1β, IL‐6, and IL‐10 during the first day of sepsis, suggesting that these cytokines may take a crucial role in the acute phase of sepsis." (PMID 33719215, 2021). "Considering the possible relationship between inflammation and CLP-induced sepsis, the levels of IL-6, IL-10, and TNF-α in the PLF and blood obtained 8 and 24 h after CLP were measured in order to assess how omentum removal could affect cytokine production in response to infection." (PMID 33815381, 2021). "They found that IL-6 and IL-10 levels were both independently associated with mortality, but that the balance of these inflammatory mediators (IL-6/IL-10 interaction) does not seem to impact either early, intermediate or late mortality in ICU patients with sepsis." (PMID 34945111, 2021). "This work reported the production of the immunosuppressive cytokine IL-10 produced by NK cells in a murine model of sepsis and in human sepsis disease, revealing a potential immunoregulatory mechanism of NK cells during sepsis that may have a crucial role in the survival of the host." (PMID 35053151, 2021). "The higher serum IL10 level in sepsis compared to all other ICU pathologies may suggest that EBV and CMV reactivation could be triggered by molecular events mediated by stress, local trauma, or unrelated infections, rather than associated with pre-existing immune suppression." (PMID 34795661, 2021). "IL‐10 plays a vital role in down‐regulating pro‐inflammatory cytokines and reducing uncontrolled inflammatory responses, which may help reduce tissue damage and improve the outcomes of sepsis patients." (PMID 32383354, 2020). "Similarly, targeting STAT3 in other pathological conditions such as sepsis could also provide a therapeutic avenue to control the expansion of MDSCs and regulate the production of IL-10, and thus, enhance immune responses." (PMID 32931721, 2020). "The sepsis patients were selected based on the fulfilment of a number of criteria indicative of immune suppression, namely the number of days following the onset of sepsis, monocytic HLA-DR expression, lymphocyte profiles, IL-6 and IL-10 levels, bacterial cultures and clinical scores." (PMID 33336293, 2020). "In addition, our data revealed that silencing circDNMT3B could contribute to the significantly increased level of d‐lactic acid, FD‐40, MDA, DAO, IL‐10 and IL‐6, in comparison to the sepsis group, while the activity of SOD was lower." (PMID 32383354, 2020). "Thus, increased IL-10 in patients of the reactivated group may somehow play a role in renal failure in sepsis." (PMID 31227794, 2019). "However, sustained elevated levels of IL-10 may be detrimental during the late phase of sepsis due to its immunosuppressive properties that may negatively impact bacterial clearance." (PMID 31500303, 2019).
Sepsis (continued). "In murine CLP-sepsis, human adipose-derived mesenchymal stem cells were able to modulate sepsis by downregulation of Th1-cell responses, associated with lower levels of pro-inflammatory cytokines (TNF, IL-1β, IL-6, IL-12, IFNγ) and higher levels of anti-inflammatory IL-10 derived from macrophages." (PMID 31114571, 2019). "Increased levels of IL-8 and IL-10 were associated with sepsis, whereas TNFα was not changed." (PMID 30555806, 2018). "In a study with 69 septic patients, the plasma levels of IL-10 were detectable with the ELISA method in heparinized blood in 39 (57%) of the enrolled subjects; the median IL-10 concentration was higher in patients with septic shock (58 pg/mL) in comparison to those with sepsis (11 pg/mL)." (PMID 29769838, 2018). "These clinical data indicate that IL‐10 may contribute to the increased percentage of Treg cells among the CD4+ T‐cell population under septic conditions, thus contributing to the immunosuppressive state associated with refractory sepsis." (PMID 30238076, 2018). "Thus, pDC favor the generation of IL-10-producing splenic DCs during sepsis." (PMID 29218051, 2017). "Therefore, higher IL-10 and lymphopenia are important in sepsis-induced immunosuppression." (PMID 28628675, 2017). "Thus, it is possible that increased CXCR4 expression during sepsis may amplify this pathway and result in enhanced IL-2, IL-4, and/or IL-10 secretion." (PMID 29232699, 2017). "Furthermore, we suggest that the balance between TNF and IL-10 may be altered in a favorable way in the initial as well as later stages of sepsis development by the combined treatment." (PMID 28261486, 2017). "Therefore, IL-10 contributes to immune suppression in sepsis and propagates secondary infections." (PMID 28241480, 2017). "Quite surprisingly, mTPOR-MBP was not able to inhibit the increase in plasma concentrations of TNF-α, IL-6 and IL-10 observed in both models, a well-known phenomenon that participates in the initiation and progression of organ damage during systemic inflammation and sepsis." (PMID 26963510, 2016). "Several studies demonstrate that the protective role of MSCs in sepsis may be attributed essentially to the soluble paracrine factors released by these cells, such as interleukin-10 (IL-10), prostaglandin E2 (PGE2), tumor necrosis factor-alpha (TNF-α)-stimulated gene/protein 6, and IL-6." (PMID 26474552, 2015). "However, whether the Notch signaling pathway in regulation of PD-1 expression is through the IL-10 during sepsis-induced immunosuppression is unclear." (PMID 26063974, 2015). "This study is part of a larger study to evaluate the characteristics of sepsis patients and its purpose is to study the relationship between gender and mortality due to sepsis and to identify differences if any between the cytokine levels specifically IL-6, IL-10 and TNF alpha between the genders." (PMID 26649014, 2015). "Furthermore, persistently high concentrations of IL-6 and/or IL-10, were associated with negative outcome of sepsis in humans." (PMID 26410584, 2015). "Interleukin-10 was recently demonstrated to be an independent mortality predictor in SAB patients with survivors having normal interleukin-10 levels but interleukin-10 has been demonstrated to be a weaker predictor of ICU mortality among sepsis patients as compared to cf-DNA." (PMID 24520336, 2014). "IL-10 has been assigned a regulatory role, which, early in the course of sepsis, could improve the outcome, whereas it may be deleterious late in the course of sepsis, suggesting a dichotomous role for this cytokine." (PMID 25182529, 2014). "However, the expression levels of IL-10 were higher in the NaHS groups than in the sepsis group." (PMID 25009602, 2014). "C-reactive protein (CRP), tumor necrosis factor-α (TNF-α) and interleukins are among the first-discovered potential biomarkers for sepsis, among which IL-6 and IL-10 may be good choices as biomarkers while CRP and TNF-α are nonspecific biomarkers for inflammation." (PMID 24977412, 2014).
Sepsis (continued). "In contrast, the CLP model of sepsis, which arises from a nidus of infection, appears to favor, at least at the level of the leukocyte transcriptome, the increased expression of immune suppressive pathways, such as IL-10 signaling; and early, short-lived activation of innate inflammatory pathways." (PMID 24788351, 2014). "Furthermore, considering the CD55 expression levels on neutrophils from WT, Il-1r−/−, Il-10−/−, and Nod2−/− mice with CLP, it is conceivable that NOD2-mediated IL-10 production suppresses CD55 expression on peritoneal neutrophils during sepsis in both IL-1β-dependent and IL-1β-independent manners." (PMID 23675299, 2013). "Therefore, the high mortality of patients during hypo-inflammatory phase of sepsis might be attributable to the effect of IL-10 on both NOD2-mediated C5a generation and immune suppression, which leads to primary and/or secondary hospital-acquired infection." (PMID 23675299, 2013). "The presence of a detectable IL-10 at days 1–2 was associated with a severe head injury (p = .03), mortality at days 28 (p = .01), and shock at days 1–2 (p = .006), but not with sepsis development (p = .3), massive transfusion (p = .36) nor major thoracic injury (p = .19) (data not shown)." (PMID 22431998, 2012). "Moreover, other IL-10 studies in murine sepsis suggest systemic over-expression of IL-10 may be deleterious due to its potential to create a state of immune paralysis by producing a TH2 state and suppressing TH1 cytokine production." (PMID 17472748, 2007). "• The three polymorphisms evaluated in the present study (the TNF-α-308 promoter polymorphism, the polymorphism in the first intron of the TNF-β gene, and the IL-10-1082 promoter polymorphism) appear not to influence outcome in patients admitted to the hospital with sepsis." (PMID 16859504, 2006). "The IL-10 -1082 SNP may modify the response to sepsis from a variety of organisms." (PMID 16611358, 2006). "All three sepsis subgroups showed significantly elevated levels of TNF-α, IL-10, HBP and higher APACHE-II scores compared with the control group (all P < 0.05)." (PMID 41737161, 2026). "Mechanistically, IFI27 suppresses Treg function and enhances ferroptosis in lung epithelial cells through inhibition of the IL-10/STAT3 signaling pathway, thereby aggravating sepsis-induced lung injury." (PMID 42099627, 2026). "Clavanin A and Clavanin-MO attenuate systemic inflammation and sepsis in murine models by downregulating pro-inflammatory cytokines such as IL-12 and TNF-α while upregulating the anti-inflammatory cytokine IL-10." (PMID 41440897, 2025). "As sepsis progresses, immune dysfunction shifts towards immune paralysis, driven by MDSC activation and IL-10 overproduction." (PMID 40421209, 2025). "IL-10 and TGF-β produced by MDSCs during latesepsis can dysregulate the functions of innate and adaptive immune cells, therebycontributing to sepsis immunosuppression." (PMID 40458301, 2025). "Current interest lies in the overexpression of cytokines such as IL-6, IL-10, and CCL2 due to their reported correlation with sepsis severity." (PMID 40178612, 2025). "In contrast, subcutaneous infection led to increased IL-10+ B cells, CD4+, CD8+ T cells, and MHCII+ macrophages, all correlating with the sepsis score." (PMID 40178612, 2025). "In EBV-associated HLH, additional studies have shown disproportionately high IFN-γ and IL-10 with low IL-6, yielding IFN-γ/IL-6 and IL-10/IL-6 ratios that robustly differentiate EBV-HLH from sepsis." (PMID 41234904, 2025). "To further delineate the effects of sepsis on PLN T cells in MLDS T1D, we determined the number of CD4+ and CD8+ T cells able to produce IFN-γ, IL-17, TNF and IL-10 in CLP+STZ and SHM+STZ mice." (PMID 41142792, 2025). "TNF, IL-18, IL-10, IL-1Ra and s-CHI3L1 were significantly higher in the septic shock group, compared with the sepsis and non-sepsis groups." (PMID 40681771, 2025).
Sepsis (continued). "These cells were also less functional in sepsis: after stimulating PBMC’s ex vivo with PMA/Io, only healthy samples had a statistically significant reduction in CD4+IL10+ T cells." (PMID 39935482, 2025). "Statistical analysis was performed on serum concentrations of CRP, IL-6, IL-1β, TNF-α, IL-10, and PDL1 from healthy individuals and sepsis patients, using a 95% CI." (PMID 40568710, 2025). "In some clinical studies, IFN-γ has the potential to improve monocyte dysfunction in sepsis patients by increasing mHLA-DR expression and TNF-α secretion while reducing IL-10 expression, thus reversing immunosuppression." (PMID 40153575, 2025). "In sepsis-induced acute lung injury, upregulation of lncRNA H19 inhibited TNF-α, IL-1β, IL-6, IL-10, and BAX to suppress pulmonary apoptosis and inflammation." (PMID 39940682, 2025). "Uniquely combines Interleukin-10-to-Lymphocyte Ratio (ILR) and lactate for sepsis prognosis (AUC = 0.860), outperforming SOFA and APACHE II scores." (PMID 41001389, 2025). "We first assessed IL-10 and TGF-β production by MDSCs.MDSCs from late sepsis mice were stimulated with LPS." (PMID 40458301, 2025). "Neonates with EONS had higher levels of inflammatory and oxidative stress markers in UCB before the onset of symptoms; UCB IL-6, IL-10, and oxidative stress markers were significantly higher in infants with EONS, even in the proven sepsis group." (PMID 40171168, 2025). "In the CLP-induced sepsis kidney injury model, the IL-2 gene exhibited low expression, whereas the CXCL8, IL-1β, TNF, IL-6, and IL-10 genes demonstrated high expression levels." (PMID 40166075, 2025). "Since proinflammatory cytokine overproduction is indicative of sepsis, we evaluated the levels of TNF‐α, IFN‐γ, IL‐1α, IL‐1ß, IL‐6, IL‐10, IFN‐ß, IL‐17A, IL‐23, IL‐27, MCP‐1, IL‐12p70, and GM‐CSF in the serum at 16 h after LPS‐induced septic shock." (PMID 39482884, 2025). "IL-10 and TGF-β are potent immunosuppressive cytokines thatmediate and sustain sepsis-induced immunosuppression in animals and humans." (PMID 40458301, 2025). "PN enhances bacterial clearance in sepsis by modulating adaptive immune responses, including suppression of TNF-α, IL-10, and IL-6 secretion, while concurrently reducing cellular apoptosis and increasing neutrophil counts." (PMID 40725434, 2025). "First, it provides a comprehensive analysis of multiple inflammatory markers, including CRP, IL-1β, IL-6, IL-8, IL-10, PCT, and TNF-α, which offers a detailed understanding of the immunomodulatory effects of ulinastatin in the treatment of sepsis." (PMID 40667510, 2025). "Our results showed that the expression of IL-10 on day +7 (P = 0.005), TNF-α and IL-6 on day +14 (P = 0.041 and P =0.010), and IL-6 on day +28 (P = 0.010) were higher in patients with sepsis than the control group." (PMID 40718494, 2025). "This meta-analysis demonstrated that ulinastatin significantly reduces mortality and inflammatory markers such as CRP, IL-1β, IL-6, IL-8, IL-10, PCT, and TNF-α in patients with sepsis compared to control group." (PMID 40667510, 2025). "The primary outcomes assessed were levels of inflammatory markers such as IL-1β, IL-6, IL-8, IL-10, CRP, PCT, and TNF-α, providing a comprehensive overview of the effectiveness of the combined therapy on inflammatory responses in sepsis patients." (PMID 40667510, 2025). "Additionally, adiponectin enhances regulatory T cell (Treg) function by upregulating FOXP3 and IL-10 expression, promoting immune tolerance which could be beneficial in sepsis through limiting the uncontrolled immune activation that is characteristic of sepsis." (PMID 40652274, 2025). "Our study addresses this gap by simultaneously evaluating sTREM-1, HMGB1, sCD14-ST, IL-10, vitamin D, and sHLA-G in patients with SIRS and sepsis." (PMID 41153764, 2025). "In the context of sepsis, NRP-1 has been shown to stabilize regulatory T cells (TReg), promoting the release of immunomodulatory cytokines such as IL-4, IL-10, and TGF-β." (PMID 40733612, 2025).
Sepsis (continued). "We demonstrate that these induced PCs contribute to sepsis-induced immune alterations by inhibiting T-cell proliferation and IFN-γ secretion ex vivo through increased IL-10 production and elevated PD-L1 expression, independently of regulatory T cells." (PMID 40155394, 2025). "It is of relevance to the effective management of sepsis that the NTCI peptide suppressed the mediators of inflammation in the blood (IL-6, IL-10, TNFα, Interferon γ, and MCP1)." (PMID 41229427, 2025). "Children with sepsis had more regulatory CD4+ T cells and memory CD4+ T cells and less CD4+IL-10+ and CD8+T-bet+ T cells than healthy children." (PMID 39935482, 2025). "Neutralizing IL-10 or TGF-β, which are key in Treg differentiation, can alleviate immunosuppression in sepsis, reduce the ratio of Tregs to CD4+ T cells, and restore the number of CD4+ T cells in the spleen, potentially increasing survival." (PMID 40153575, 2025). "In humans, IL-4 and IL-10 levels rise during the recovery phase of SIRS and sepsis, although they typically remain lower than pro-inflammatory cytokines such as IL-6 and TNF-α." (PMID 40584120, 2025). "We detected S100A9 protein at both IL-10 and TGF-βpromoters in MDSCs during late sepsis and levels of S100A9 bindingsat these promoters were significantly reduced after the knockdown ofS100A9 in MDSCs from wild-type mice." (PMID 40458301, 2025). "Compared to the sham group, the levels of IL-6, IL-1β, IL-10 and TGF-β in the sepsis group and the placebo group were also significantly elevated (p < 0.01)." (PMID 41584453, 2025). "During the late phase of sepsis, dendritic cells (DCs) exhibit a tolerogenic/exhausted phenotype (low co-stimulatory molecules, high PD-L1/ICOS-L, secretion of IL-10, expression of IDO1)." (PMID 40806563, 2025). "Further, CD4+IL10+ T cells, including IL10+ regulatory CD4 T cells, were lower in sepsis compared to healthy patients." (PMID 39935482, 2025). "This multicentric observational prospective study aims to evaluate blinding the genetic expression kinetics of different molecules involved in the inflammatory process, IL10, PD1 and WT1, to search for a possible molecular predictive marker of sepsis." (PMID 41013722, 2025). "Early recognition of late-sepsis biomarkers, such as decreased lymphocyte count, increased MDSC production, increased IL-10 levels, changes in GPR18 expression, and decreased HLA-DR expression, will help with targeted diagnoses and treatments." (PMID 38255280, 2024). "The determination of CRP and procalcitonin (PCT) is higher in the sepsis group compared with patients with ACLF; the serum concentrations of IL-6 and IL-10 are higher in severe sepsis and different from those in subjects with ACLF or with stable cirrhosis." (PMID 39337069, 2024). "Although in animal sepsis models, the use of specific neutralizing antibodies blocking the activity of TNF-α and IL-10 significantly improved the prognosis of sepsis, neutralizing antibodies to TNF-α in clinical trials did not yield satisfactory results." (PMID 38313013, 2024). "This intervention resulted in reduced levels of biochemical organ injury markers and inflammatory cytokines (IL-6, IL-10, and TNF-α), indicating attenuation of the sepsis-induced inflammatory response." (PMID 38888975, 2024). "Sepsis-induced inflammatory mediators, such as TNF-α, IL-6, and IL-1β, inhibited the protective anti-inflammatory cytokine IL-10." (PMID 38926458, 2024). "We focused on six cytokines that play a major role in sepsis: IFN-γ, IL-1β, IL-6, IL-10, IL-18 and TNF6." (PMID 38191855, 2024). "As IL-10 administration increases the risk for bacterial infections, taking into consideration that the main causes of death in SCI patients have been septicemia and pneumonia, treatment of these patients with IL-10 may be dangerous without careful monitoring and appropriate antimicrobial therapy." (PMID 38248028, 2024).